CD4 (CD4 molecule)
Diseases named in the same sentence as CD4 in open-access papers (continued):
Sharing a sentence is not in itself a finding about the gene and the disease.
skin infection (26 papers, 2010 to 2025). An inflammatory process affecting the skin, caused by bacteria, viruses, parasites, or fungi. "We showed previously that after repeated infection, M2-like dermal APCs conditioned within the skin infection site, which is rich in IL-4 and IL-10, were associated with decreased CD4+ T cell responsiveness in the skin draining lymph node." (PMID 25974019, 2015). "Additionally, patients with hyper-IgE syndrome who lack the ability for Th17 CD4+ T cell differentiation are highly susceptible to SA skin infections, and HIV+ patients are more susceptible to MRSA skin infections possibly due to decreased IFN-γ production from SA Ag-specific CD4+ T cells." (PMID 32343740, 2020). "Using a murine model, repeated infections result in IL‐10‐dependent CD4+ T‐cell hyporesponsiveness in the skin‐draining lymph nodes (sdLN), which could be caused by an abundance of eosinophils and connective tissue mast cells at the skin infection site." (PMID 26679416, 2016). "T6030504 was analyzed further in several assays involving primary immune cells (PBMCs), whole blood, and complex immune-responsive 3D-skin infection models, including CD4+ T cells." (PMID 35208698, 2022). "For this purpose, the isolated CD4+T cells were incubated with T6030504 or mock treated for 6 h before addition to the 3D-skin infection model." (PMID 35208698, 2022). "We previously showed that immune cells from human blood, like PBMCs and CD4+-T cells, activate dermal fibroblasts in 3D-skin infection models to engage in anti-microbial defense." (PMID 35208698, 2022). "CD4+ IL-17-producing TRM cells can mediate long-term protective immunity against C. albicans skin infection." (PMID 32093731, 2020). "In contrast, studies in murine models indicate that CD8+ αβ-T cells are dispensable during S. aureus infection, whereas there is an abundance of data, in empyema and skin infection models, supporting a central role of CD4+ T cells." (PMID 33291260, 2020). "In a different study, vaccination with a multiple antigen presenting system with six staphylococcal proteins led to the differentiation of CD4+ T cells that produced both IFNγ and IL-17A, which mediated protection against both bloodstream and skin infections." (PMID 33291260, 2020). "The other patient, an 8 year old boy with an absolute CD4 count of 6 cells/mm3 (1%) and serum IgE level of 59.300 kU/L, had generalised pruritic skin lesions and was diagnosed with scabies." (PMID 28443591, 2017). "LCs may function in the context of skin infections to present external antigens to activate CD4 + T cells or to present CD4 + T cells." (PMID 39962262, 2025). "However, the inflammation-healed skin of C57BL/6 mice was found to produce similar or higher numbers of CD4+ TRM cells than CD8+ TRM cells following a skin infection with Candida albicans or the cowpox virus." (PMID 32508808, 2020). "Indeed, in the absence of IL-4Rα signaling, significantly greater numbers of CD3+CD4+ T cells were present in the skin infection site of 4x IL-4RαKO, compared to 4x WT mice (p<0.0001)." (PMID 27505056, 2016). "According to our analysis, monocyte-derived inflammatory DCs are by far the most abundant DC subtype in HSV-infected skin and therefore, may be the major drivers of peripheral CD4+ TEFF-cell responses during HSV-1 skin infection." (PMID 25121482, 2014). "CD4+ T cells were demonstrated to be prevalent in the skin of ordinary patients with scabies, while crusted scabies lesions had an increased number of CD8+ T cells compared to minimal CD4+ cell count." (PMID 38673000, 2024). "Histological analysis has documented the infiltration of CD4+ T cells and CD8+ T cells in the skin of patients with scabies, thus supporting the implication of the cell-mediated immune response to mites in the pathogenesis of the disease." (PMID 38673000, 2024). "The frequency of skin infections correlated with the proportion of CD62L+ T cells, naïve CD4+ and CD27+ CD8+ T cells and with activated B cells." (PMID 30477583, 2018).
skin infection (continued). "The skin infection frequency and need for antibiotic usage correlated with the proportion of CD62L+ T cells, naïve CD4+ and CD27+ (intermediate memory) CD8 cells and with activated B cells." (PMID 30477583, 2018). "Here, we show key differences in the regulation of effector activity between CD4+ and CD8+ T-cells during skin infection with HSV-1." (PMID 25121482, 2014). "Here we reveal that upon skin infection with herpes simplex virus, migratory CD103+ DCs from draining lymph nodes were more potent at inducing Th17 cytokine production by CD4+ T cells than CD8+ DCs." (PMID 24637385, 2014). "Our results demonstrate that the zwitterionic WTA of S. aureus induces CD4+ T-cell proliferation in an MHCII-dependent manner, which in turn modulates abscess formation in a mouse skin infection model." (PMID 20949105, 2010). "Higher levels of functional selectin ligands on Th1 cells than Th2 cells have been linked to a difference in migration into inflammatory sites and similar selectin ligand differences have also been observed among CD4+ and CD8+ T cells migrating into sites of skin infection." (PMID 29671006, 2018). "Interestingly in this respect, IFN-γ can exert long-range effects on target cells located as far as 80 μm from CD4+ TEFF-cell-APC conjugates, as recently shown for skin infection with Leishmania major." (PMID 25121482, 2014). "However, whilst the absence of IL-4Rα resulted in increased numbers of CD4+ cells in the skin infection site and the sdLN, the cells in the sdLN remained hypo-responsive in vivo to stimulation with parasite antigen similar to 4x WT mice." (PMID 27505056, 2016). "In a skin infection model, infiltrating CD8+ T cells, but not CD4+ T cells, upregulate CD69 on their cell surfaces after skin entry which serves to retain the cells in the skin and later differentiate into resident memory T cells." (PMID 36275685, 2022).
steatosis (26 papers, 2010 to 2025). Increased lipid within the cytoplasm of cells. "Decedents with a CD4 T-lymphocyte count > 200 cells/μL were also more likely to be normal/overweight (OR: 9.45; 95% CI: 0.95–94.48), another risk factor for steatosis." (PMID 39822280, 2024). "A preserved CD4 count and being female conferred the highest risk for steatosis, underscoring the need for screening in this subgroup and further research to delineate risks in a Southern African population." (PMID 39822280, 2024). "A CD4 T-lymphocyte count of > 200 cells/μL was associated with an increased risk for steatosis (OR: 3.69; 95% CI: 1.19–11.44), while being virologically suppressed (viral load < 200 RNA copies/mL) was not (OR: 1.19; 95% CI: 0.40–3.54)." (PMID 39822280, 2024). "A nadir CD4 < 200/μl was associated with increased risk of steatosis." (PMID 34522873, 2021). "All four CD4+ T cell subsets, T-bet+ (Th1), Eomes+ (cytotoxic), FoxP3+ (Tregs), and RORγt+ (Th17), were elevated in MASH livers compared to isolated steatosis, with T-bet+ CD4+ T cells showing a statistically significant increase." (PMID 40631180, 2025). "After a high-fat diet (HFD), immunodeficiency mice implanted with human immune cells develop steatosis, liver inflammation, and fibrosis, along with increased liver and peripheral blood CD4+ memory T cells." (PMID 37020540, 2023). "In the intralobular area, CD8+ and CD4+ lymphocytes presented significantly higher values in cases with more severe steatosis (p=0.023 and p=0.012, respectively)." (PMID 33664397, 2021). "In summary, we described a humanized mouse model for diet-induced NAFLD and showed that subsets of CD4+ T cells, specifically IL-17A-secreting Th17 and IFNγ -secreting Th1, play a key role in the progression of steatosis to fibrosis." (PMID 33013934, 2020). "As hepatic inflammation is one of the main factors differentiating simple steatosis from progressive steatohepatitis, the investigation of the hepatic infiltration of CD4+ and CD8+ T cells showed significant differences in the ratio of these cell types." (PMID 30538805, 2018). "In liver samples, CD4+ T cells, Kupffer cells and monocytes were characterized near hepatocellular necrosis and steatosis in the presence of pro-inflammatory cytokines, IFN-γ and TNF-α." (PMID 28006034, 2016). "Interestingly, the level of IL-10 [MFI in CD4+] and IL-10 [MFI in CD4+CD25+] differentiated patients with simple steatosis in early MASLD from advanced MASLD patients (p < 0.01, p < 0.02, respectively)." (PMID 40918132, 2025). "In MAFLD, CD4+ memory T cell subsets are crucial in the transition from steatosis to fibrosis." (PMID 37020540, 2023). "Nadir CD4 cell count < 200/μl, higher BMI, higher liver stiffness, higher CD8+ cell counts, lower platelets and younger age were also independent risk factors of de novo steatosis." (PMID 34522873, 2021). "On the other hand, in a mouse model of diet induced steatosis, ATG7-deficient T cells show increased expression of IFN ɣ and IL-17 in both CD4+ and CD8+ T cells, suggesting differentiation bias toward Th1 and Th17 phenotypes in CD4+ T cells." (PMID 31632966, 2019). "The median CD4 count among HIV-infected patients with steatosis was 176 cells/mm3 (IQR: 91, 253)." (PMID 25668620, 2015). "Finally, in the pediatric group concerning steatosis in the portal-periportal area, total lymphocyte count showed a profile tending to higher values with a more severe steatosis grade, while only CD4+ lymphocytes showed significantly higher values in cases with steatosis grade 3 (p=0.023)." (PMID 33664397, 2021). "Most remarkable, only those severe cases displayed Foxp3+ and IL-17A+ cells; one possible explanation for this observation could be that CD4+ lymphocyte frequency is very low in steatosis grade 1 and 2 cases, therefore these subpopulations may be underrepresented in these stages." (PMID 33664397, 2021).
steatosis (continued). "Among the cytokines tested, IL-17A had the greatest fold-increase in the peripheral blood of HIL mice on the HFHC diet and decreased significantly when these mice were depleted of CD4+ T cells, implying that IL-17A-producing Th17 CD4+ T cells may contribute to steatosis-to-fibrosis progression." (PMID 33013934, 2020). "Several parameters distinguished patients with simple steatosis at the early MASLD stage from those with steatosis with inflammation – advanced MASLD, including Foxp3+ [% of CD4+CD25+]; IL-10 [MFI in CD4+ and CD4+CD25+ populations]." (PMID 40918132, 2025). "In steatosis and MASH, intrahepatic B cells secrete elevated levels of IL-6 and TNFα, which promote the activation of CD4 cells and their differentiation into Th1 cells." (PMID 39372417, 2024). "In steatosis and MASH, intrahepatic B cells secrete elevated levels of IL-6 and TNF-α, which promote the activation of CD4 T cells and their differentiation into Th1 cells." (PMID 39372417, 2024). "Compared with those in the control group, patients with simple steatosis exhibited low expression of TLR9 on T cells, which affected intrahepatic CD4+ T cells and peripheral CD4+ and CD8+ T cells and decreased production of proinflammatory factors by T cells." (PMID 38685971, 2024). "Inhibit the CD4+ and CD8+ T cells recruitment in liver, improve steatosis, inflammation and fibrosis in MASH progression." (PMID 37361209, 2023). "Pediatric cases with worse steatosis showed high P/P CD4+ (p = 0.023) and intralobular CD8+ (p = 0.027) and CD4+ cells (p = 0.012)." (PMID 33664397, 2021). "Depleting human CD4+ cells in this model reduces liver inflammation and fibrosis, but not steatosis by secreting pro-inflammatory molecules such as IFN- γ and IL-17A." (PMID 37020540, 2023). "However, in mice lacking either CD4 or CD8 T-cells, the pathological changes associated with chronic hepatitis were resolved following rVV-N25 immunization, and the steatosis score of rVV-N25-treated mice was significantly lower than that of control mice." (PMID 23284733, 2012). "Taken together, these results demonstrate that CD4+ T cells, but not CD8+ T cells or CD14+ monocytes, contribute to the development of NAFLD-induced inflammation and steatosis-to-fibrosis progression." (PMID 33013934, 2020). "In vivo depletion of human CD4+ T cells in HIL mice reduced liver inflammation and fibrosis, but not steatosis." (PMID 33013934, 2020).
airway hyperresponsiveness (25 papers, 2005 to 2026). "Investigations into the causes of ERD using multiple animal models have revealed Th2 CD4+ T cells to be closely linked to the increased inflammation, mucus, and airway hyperresponsiveness observed in ERD." (PMID 32849580, 2020). "They found that TDI-exposed mice had higher numbers of BAL eosinophils, CD4+ T cells and ILCs, with a predominant type 2 response, and tended to have airway hyperresponsiveness." (PMID 38295127, 2024). "In mice, IL-13 treatment induced airway hyperresponsiveness and led to increased numbers of IL-17-producing CD4+ T cells." (PMID 32849611, 2020). "Depletion of CD4+ T cells attenuated airway hyperresponsiveness and lung eosinophil count in a CD4 antigen induced mouse model." (PMID 32580518, 2020). "IL-4 was important in CD4+ lymphocyte differentiation and the production of IgE,while IL-13 drived airway hyperresponsiveness, mucus production, and subepithelial fibrosis." (PMID 31747880, 2019). "Collectively, these observations reveal that GSNOR inhibitors are effective not only in reducing airway hyperresponsiveness but also in limiting lung inflammatory responses mediated by CD4+ Th2 cells." (PMID 23936192, 2013). "Treatment with anti-CD4 monoclonal antibody or deletion of the IL-13 gene improves ovalbumin-induced airway hyperresponsiveness and reduces airway inflammatory cells in transgenic mice." (PMID 23382928, 2013). "It is well-known that an unbalanced T-cell immune response can be harmful due to an excessive reaction of CD8+ T-cells, which leads to lung tissue damage, or a Th2-biased CD4+ T-cell response resulting in excessive mucus production and airway hyperresponsiveness." (PMID 37511205, 2023). "Cytokines, inflammatory cells and inflammatory mediators interact with each other, resulting in the infiltration of a large number of airway eosinophils and CD4+ T cells, as well as mucus hypersecretion, airway hyperresponsiveness, airway remodeling and increased IgE production." (PMID 25289045, 2014). "Thus, lower CD88-expressing alveolar macrophages, CD4− T cells, and B lymphocytes in ova-ova March1−/− relative to WT in our study may further explain and contribute to the milder airway hyperresponsiveness in March1−/− mice." (PMID 29854835, 2018). "Although AM have been suggested to prevent development of airway hyperresponsiveness upon OVA challenge, AM are also known to produce proinflammatory cytokines that enhance Th2 cytokine production by pulmonary CD4+ T lymphocytes." (PMID 23815813, 2013). "Other report had also pointed out that peripheral blood IFN-γ-producing CD4+ and CD8+ T cells from non-atopic asthmatic children were increased in relation to atopic children and inversely associated with eosinophils or airway hyperresponsiveness." (PMID 23253516, 2012).
cervical intraepithelial neoplasia (25 papers, 2009 to 2026). "Women who were smokers at baseline were more likely to develop cervical dysplasia (aHR 1.77; 95% CI 1.29–2.42), while those with higher CD4 cell counts at registration into the SHCS had a lower cervical dysplasia risk (per 100 cells/μL increase; aHR 0.95; 95% CI 0.90–1.00)." (PMID 41216952, 2025). "Interestingly elevated IL17 production by CD4+ T-cells has recently been demonstrated in HPV-associated cervical intraepithelial neoplasia." (PMID 27160146, 2016). "Few studies investigated the relationship between CD4,CD8,IL-10, and high-risk human papillomavirus (HPV) with risk of cervical intraepithelial neoplasia (CIN)." (PMID 41142594, 2025). "Women living with HIV should be routinely screened for cervical dysplasia, especially those with low CD4 lymphocyte count or high HIV viral load." (PMID 35630489, 2022). "The relationship between a low CD4 baseline or nadir lymphocyte count and cervical dysplasia is still controversial." (PMID 35630489, 2022). "The objective of this study was to evaluate the production of cytokines in helper T (CD4+) lymphocytes during immunotherapy with pegylated IFN-α in patients with cervical intraepithelial neoplasia (CIN)." (PMID 25764160, 2015). "The associations between low CD4 counts, HPV and cervical dysplasia have been previously documented." (PMID 19664216, 2009). "Lower CD4 counts were strongly associated with higher rates of cervical dysplasia, carcinoma in situ, and cancer, independent of HIV RNA." (PMID 41689274, 2026). "As CD4 counts drop below 200 cells/μL, there is a 2-fold increase in the incidence and prevalence of cervical preinvasive lesions such as cervical intraepithelial neoplasia (CIN) and low-grade squamous intraepithelial lesion (LSIL), when compared to those with CD4 counts > 500 cells/μL." (PMID 29075090, 2017). "We have previously reported an increase of CD4+NKG2D+ T cells in patients with low-grade cervical intraepithelial neoplasia, which might be the result of a chronic exposure to viral and/or pro-inflammatory factors." (PMID 26486970, 2015). "In addition, it has also been shown that with decreasing numbers of CD4+ T-cells, there is an increase in both frequency and severity of cervical dysplasia in HIV-infected women." (PMID 26401120, 2015). "Interestingly, we recently reported a substantial increase in the frequency of CD4+NKG2D+ T cells in patients with cervical intraepithelial neoplasia grade-1." (PMID 26486970, 2015). "As some studies have shown, HIV control with antiviral agents, CD4 counts, and HIV viral load are factors that affect HPV infection and outcomes of cervical dysplasia treatments." (PMID 40095809, 2025). "The rates of high-grade cervical dysplasia and HPV coinfection are directly related to HIV viral load and inversely related to CD4 count." (PMID 29075090, 2017). "Of 901 HIV-infected women, 80 women were excluded as 18 women did not received Pap smear screening, 12 women did not have an intact cervix at baseline, 31 women had a previous diagnosis or treatment of cervical intraepithelial neoplasia, and 19 women had no documentation of CD4+ count." (PMID 21211065, 2011). "The concomitant WHO recommendation to initiate HAART when asymptomatic at CD4 count ≥350 cells/μl, instead of at CD4 count ≥200 cells/μl, may offer women the possibility to ensure continuous cervical screening during regular follow up, thereby preventing HPV 16 and HPV 18 induced cervical dysplasia." (PMID 27053945, 2016).